RAC1 (Rac family small GTPase 1)
Diseases named in the same sentence as RAC1 in open-access papers (continued):
Sharing a sentence is not in itself a finding about the gene and the disease.
cancer (continued). "Recently, more studies have demonstrated the role of EGFR-stimulated activation of Rac1 in cancer cell migration, invasion, and survival." (PMID 30544910, 2018). "Rac1 is the best-characterized member of this subfamily with strong evidence for Rac1 dysregulation in cancer." (PMID 30261690, 2018). "Due to its well-established role in controlling cytoskeleton dynamics, studies have been focused on revealing the role of Rac1 in cancer metastasis." (PMID 30544910, 2018). "The oncogene Rac Family Small GTPase 1 (RAC1) is closely associated with tumorigenesis, tumor progression and therapy resistance, and RAC1 alternative splicing is important for its regulatory role in cancers.." (PMID 29843604, 2018). "Rac1 and RhoA/C contribute to metastasis by regulating separate types of invasive behavior in cancer cells, with Rac1 driving integrin-dependent, mesenchymal-type movement and RhoA/C driving integrin-independent, amoeboid movement." (PMID 29769144, 2018). "Their study showed that TGF-β1 secreted by cancer cells activates the TGF-β receptor/RAC1/SMAD–dependent signaling pathway in mesothelial cells." (PMID 29861857, 2018). "The tumor suppressor Nischarin interacts with a number of signaling proteins such as Integrin α5, PAK1, LIMK1, LKB1, and Rac1 to prevent cancer cell migration." (PMID 29415725, 2018). "A major role of RAC1 is as a master regulator of cell migration, which is of particular importance to metastasis and angiogenesis in cancer." (PMID 29329780, 2018). "ARHGAP15 immunoreactivity was frequently detected in the cytoplasm of carcinoma cells, and was positively correlated with that of Rac1 and androgen receptor labeling index." (PMID 29534468, 2018). "Rac1 activity has been shown to be important for proliferation and cell cycle regulation of cancer cells." (PMID 28410221, 2017). "These processes are controlled entirely or in part by TGF-β and the small RHO GTPase RAC1 with both proteins acting as tumor promoters in late-stage cancers." (PMID 28499439, 2017). "Previous studies have shown that miR-124 inhibits cancer cell invasion and metastasis by targeting other molecules, including slug, Rac-1, SMYD3, SphK1, and ROCK1." (PMID 28270130, 2017). "Cdc42 stimulates filopodia formation, RhoA induces the formation of stress fibers, and Rac1 induces lamellipodia formation, all of which play critical roles in cancer cell invasion and metastasis." (PMID 28423650, 2017). "Here, we showed that the mRNA of integrin alpha V, integrin beta 3, α-actinin and Rac-1, as well as the protein level of α-actinin and active Rac-1 of HUVECs, were elevated after interaction with cancer cells." (PMID 28173828, 2017). "The “mesenchymal” movement (elongated movement of cancer cells) requires activation of RAC1, whereas rounded/amoeboid movement engages specific Cdc42 signaling pathways." (PMID 27902969, 2017). "We recently showed that tumor cell-expressed TRAIL and TRAIL-R2 promote cancer progression, invasion, and metastasis by cancer cell-autonomous activation of Rac1 via the MPD of TRAIL-R2 independently of FADD." (PMID 28212753, 2017). "Given the crucial role of RAC1 in survival and RAS-mediated transformation, and of RAC1 and RAC1b in modulating the TGF-β pathway, therapeutic targeting of TGF-β signaling in cancer cells with inhibitors of RAC1 and/or RAC1b provides an exciting perspective." (PMID 28499439, 2017). "Abnormal Rac1 activation has been found in several cancers and promotes cancer cell motility, invasion, and metastasis." (PMID 28104793, 2017). "The nuclear localization of the STAT3‐NF‐κB‐IκBα complex was recently shown to be regulated by Rac‐1 in starved cancer cells." (PMID 28264935, 2017). "Although this compound was used to study the mechanism of action and the effect on cancer cells of a novel Rac1 inhibitor family, we are aware of its limitations for further clinical development." (PMID 29228706, 2017).
cancer (continued). "The N-terminal WVLGE sequence promotes activation of Rac1 and subsequent host cancer cell proliferation." (PMID 28549350, 2017). "Previously, we identified ZINC69391 and its analog 1A-116 as small molecules that inhibited Rac1-GEF interactions reducing Rac1 activation levels on different cancer cells." (PMID 29228706, 2017). "These previous reports, taken together with data shown here, highlight the numerous signaling pathways that can converge on Rac1 to promote dissemination of cancer cells." (PMID 28666462, 2017). "Nevertheless, we previously showed that the semi-automatic method that we used as a substitute, produced reliable results when we analyzed the effect of inhibitors or siRNA against EGFR, MMP3 or the Rho GTPases Rac1 and Rho in cancer cells." (PMID 29237412, 2017). "Recent studies have also revealed an unexpected role for RAC1 in the response of cancer cells to DNA damaging agents." (PMID 28499439, 2017). "Control cancer cells displayed low Rac1 levels, whereas PRPF-transfected cells showed significantly elevated (2.5-fold increased) Rac1 levels." (PMID 28915620, 2017). "High levels of ROS have been shown to have anti-cancer effects by inducing cell cycle arrest and apoptosis via several mechanisms including Rac-1/NADPH oxidase pathway induction." (PMID 28160777, 2017). "Together, these studies suggest that targeting Rac1 is a viable therapeutic strategy for a number of cancers." (PMID 28410221, 2017). "Our study of the functional interplay between HACE1 and Rac1 in cancer thus sheds a new light on the molecular mechanism of Rac1 ubiquitylation by HACE1 and the impact of its cancer-associated mutations in cell proliferation." (PMID 28317937, 2017). "As such, a thorough understanding of the molecular mechanisms involved in dictating Rac1 anti- versus pro-metastatic effects are required to aid the development of effective anti-cancer therapies that spare the anti-metastatic functions of Rac1." (PMID 27314616, 2017). "The importance of Rac1 in cancer is further demonstrated by the reported deregulation of Rac1 protein level and activity in a variety of tumors, which, in turn, facilitates tumor initiation, progression and metastasis." (PMID 27442895, 2017). "Until recently, overexpression of both Rac1 and its splice variant Rac1b, together with deregulation of Rac1 regulators was considered the major mode of Rac1 signaling perturbation in cancer." (PMID 27442895, 2017). "A previous report has suggested that Rac1 contributes to cancer cell proliferation via cyclin D1 induction." (PMID 26910843, 2016). "Rac1 was reported to stimulate lamellipodium formation and contribute to cancer cell invasion by regulating activation of WAVE2 signaling complex." (PMID 26933917, 2016). "Unbiased gene ontology mining uncovered several cancer-associated/oncogenic proteins with elevated expression in MDCKYBX1 exosomes, including signalling proteins (K-Ras, RhoC, Rac1, and H-Ras)." (PMID 26919098, 2016). "As TGF-β mediated Rac1/RhoA activation was reported to be involved in cancer metastasis, these inhibitors can be possible therapeutic reagents." (PMID 27027347, 2016). "Ect2, which has activity for multiple members of the Rho GTPase family including RhoA, Rac1 and Cdc42, has been recognized as an oncogene in human cancer since 2010, being aberrantly overexpressed and mislocalised in various types of tumors." (PMID 27104658, 2016). "In this study, we found that GLS2 but not GLS1 binds to small GTPase Rac1 and inhibits its interaction with Rac1 activators guanine-nucleotide exchange factors, which in turn inhibits Rac1 to suppress cancer metastasis." (PMID 26751560, 2016). "When considering the contribution of Rac1 signalling to cancer dissemination, a challenge facing the field is accounting for its contrasting effects on migration and invasion." (PMID 26887924, 2016).
cancer (continued). "The Rac1 signaling is frequently activated in various types of cancer, in which it plays a critical role in promoting migration, invasion and metastasis of cancer cells." (PMID 26751560, 2016). "Two other family members, RhoC and RhoT1, present a number of published mutations in cancer samples and cell lines, with the S73 residue a hotspot in RhoC, while mutations in RhoT1 include a P30L mutation, which by homology may have similar effects to the Rac1 P29S mutation." (PMID 27104658, 2016). "Decreased invasion caused by AKR1C1 knockdown suggests a novel role of AKR1C1 in cancer invasion, which is probably due to the regulation of Rac1, Src, or Akt." (PMID 27698389, 2016). "Although Rac1/Cdc42 and RhoA have antagonistic functions, their coordination of their activities is essential for cell motility and cancer metastasis." (PMID 27384474, 2016). "Rac1 is most important regulator in cancer invasion and metastasis, while the efficient inhibitor is not applied in clinical even extensively investigation were done." (PMID 26933917, 2016). "In fact, it has been shown that Twist1 induces the motile stem-like cancer cell phenotype via the activation of the Twist1-let-7i-NEDD9 axis leading to RAC1 activation." (PMID 27074574, 2016). "Rac1 is frequently activated or overexpressed in various types of cancer, including HCC, and has been reported to play a critical role in promoting cancer cell migration, invasion and metastasis mainly through its regulation of actin dynamics." (PMID 26751560, 2016). "PAK1 and Rac1 reportedly play important roles within cancer cell signaling networks and contribute to invasive and metastatic phenotypes." (PMID 27027431, 2016). "Other signaling pathways triggered by the interaction of platelets with cancer cells further increased the expression of Twist1 and contributed to the formation of a migratory cancer cell presumably through the induction of RAC1." (PMID 27074574, 2016). "The results showed that Rac1 expression in metastatic tumor tissue was much higher than in prime cancer tissue." (PMID 27791203, 2016). "We use the protein RAC1 as an example to show how inhibition by aspirin leads to anti-inflammation and anti-cancer effect." (PMID 26989626, 2016). "Given that cell migration plays an important role in many physiological and pathological processes, including tumor metastasis, we examined the effect of Rac1 inhibition on cancer cell migration in vivo." (PMID 25888632, 2015). "Downstream signaling of nestin [cyclin-dependent kinase 5 (CDK5) and Ras-related C3 botulinum toxin substrate 1 (Rac1)] functions in cancer to modulate cellular behaviors." (PMID 25371063, 2015). "This raises the possible correlations and importance between GIT1 and Rac1/Cdc42 in regulating cancer progression." (PMID 26462147, 2015). "Accordingly, cancer cell migration was inhibited more efficiently by simultaneous inactivation of Rap1 and Rac1 with Rap1N17 and Rac1N17, respectively." (PMID 25888632, 2015). "According to our in vitro functional assays, GIT1 regulates cancer cell mobility through Rac1/Cdc42 activation in NSCLC cells." (PMID 26462147, 2015). "This simulation platform served as a visualization tool to predict the impact on pathway dynamics upon manipulating Rac1-Bcl-2 interaction in a cancer context." (PMID 26430964, 2015). "Cytoskeleton is associated with EMT and cytoskeletal reorganization is a prerequisite for cell motility and cancer cell invasion, and members of Rho GTPases including RhoA, Rac1 and Cdc42 play an important role in EMT as well." (PMID 26452029, 2015).
cancer (continued). "While questions remain regarding the mechanisms underlying Tβ4 activity, this work provides clear evidence of Rac1 and Rap1 GTPase activation by Tβ4 in tumor metastasis and cancer cell migration." (PMID 25888632, 2015). "To re-affirm the effect of Rac1 inhibition on cancer cell migration, H/R-experienced cells were incubated with NSC23766." (PMID 25888632, 2015). "Rac1 and Rap1 activity, as well as cancer cell migration, increased following induction of Tβ4 expression in normoxia- or H/R-experienced cells, but were barely detectable in Tβ4-depleted cells." (PMID 25888632, 2015). "Rac1 plays a crucial role in regulating cancer cell motility by virtue of cycling between inactive GDP-bound and active GTP-bound forms (i.e., GTP-Rac1)." (PMID 25860930, 2015). "In summary, we show that simvastatin suppresses the SASP and its cancer-promoting effects by repressing Rac1 and Cdc42 activation." (PMID 26658759, 2015). "Signaling by small guanosine triphosphatases (GTPase), Rap1/Rac1, is one of the major pathways controlling cancer cell migration and tumor metastasis." (PMID 25888632, 2015). "Rap1 is also activated by treatment with a Rac1 inhibitor through a Tβ4-mediated compensatory feedback mechanism in tumor metastasis and cancer cell migration." (PMID 25888632, 2015). "Among these 43, we found splicing events in the transcripts encoding IGFR, BIN1, RAC1 and TNC, which were extensively studied and found to exhibit a role in either tumorigenesis or cancer progression." (PMID 25908786, 2015). "In multiple melanomas, SDF-1α increases homing, adhesion and invasiveness of cancer through the activation of GTPases of the Ras superfamily, RhoA and Rac1." (PMID 26231656, 2015). "Then, we focus on H/R-experienced cancer cell migration and metastasis, which are regulated by crosstalk between Rap1 and Rac1 via Tβ4 expression." (PMID 25888632, 2015). "To assess the effect of compensatory feedback activation of Rap1 on cancer cell migration, we treated cells with Rap1N17 and/or Rac1N17 to inhibit Rap1 and Rac1, respectively." (PMID 25888632, 2015). "Together, these data are consistent with a role for Tβ4-mediated activation in cancer cell migration via its regulation of Rap1 and Rac1 GTPase activation." (PMID 25888632, 2015). "The greatest inhibition of cancer cell migration was seen following simultaneous inactivation of Rap1- and Rac1-GTPase." (PMID 25888632, 2015). "Rap1 was activated in response to Rac1-specific inhibition, leading to an incomplete inhibition of in vivo tumor metastasis and in vitro cancer cell migration." (PMID 25888632, 2015). "The results of the present study suggest the use of the Rac1 inhibitor to inhibit the activation of dormant cancer cells when the using of the ROCK inhibitor is inevitable for the clinical purposes." (PMID 24523903, 2014). "Campbell and colleagues showed that a common predicted target of miR-206 and miR-106a, PREX, is essential for metastasis formation in several cancer types by influencing physical migration processes through effects upon Rac1-driven motility." (PMID 24977165, 2014). "The overexpression of these genes provides an opportunity for oncolytic viruses such as oncolytic NDV, which require the Rac1 protein in their replications in human cancer cells." (PMID 25243137, 2014). "The antimigratory and anti-invasive activities of (-)-oleocanthal were associated with suppression of activation of Brk, paxillin, and Rac1 in response to HGF stimulation in MDA-MB-231 cancer cells." (PMID 24849787, 2014). "With these five functional domains, IQGAP1 is able to bind Rac1 and Cdc42, β-catenin, E-cadherin, calmodulin and components of the mitogen-activated protein kinase pathway, all of which are involved in cancer development." (PMID 24763314, 2014). "The actin cytoskeleton dynamics mechanism in tumor biology behavior, as the regulation of the actin cytoskeleton in cancer prevention and control in the sense Rac1, Pak1 and Rock1 is worth studying." (PMID 23298303, 2014).
cancer (continued). "The model provides the first step towards understanding how different levels of the small GTPases, RhoA and Rac1, in a cell govern phenotypic plasticity during carcinoma metastasis under the influence of external signals in the tumor microenvironment." (PMID 25245029, 2014). "Inhibition of Rac1 signaling in the treatment-resistant carcinoma cells can interrupt metastatic process due to anoikis restoration and decrease of cell migration." (PMID 25594058, 2014). "It seems that attenuation of Rac1 signaling in carcinoma cells can diminish their metastatic and invasive abilities." (PMID 25594058, 2014). "It has been recently reported that targeting of RAC1 protein suppresses human non-small cell lung adenocarcinoma cancer stem cell activity." (PMID 24146998, 2013). "Treatment with AR-A014418 decreased lamellipodia formation in cancer cells at the wound edge and resulted in diffuse cytoplasmic distribution of Rac1 and F-actin." (PMID 23408967, 2013). "Rac1, which has been shown to be involved in cancer cell metastasis, is highly expressed in aggressive HCC cell lines and its activity correlated with cell motility and cytoskeleton polymerization." (PMID 24274578, 2013). "Concomitant with these changes, treatment with AR-A014418 decreased the Rac1-GTP (active form) in cancer cells stimulated to multiply by the regenerating wounds." (PMID 23408967, 2013). "Small G protein RAC1 is the main member of Rho family which play important role in regulating migration of cancer cells." (PMID 23613900, 2013). "Recent study showed that Rac1 was required for NDV replication in human cancer cells, and this finding established a link between tumourigenesis and sensitivity to oncolytic virus." (PMID 23586025, 2013). "The results presented here demonstrate an inhibition of cancer cell proliferation in vitro and in vivo following Rac1/Cdc42-inhibition." (PMID 24040362, 2013). "Active migration of tumor cells is a prerequisite for tumor progression and metastasis and reports show that EGF-induced cancer cell migration can be inhibited by suppressing Cdc42/Rac1 signaling pathways." (PMID 24040362, 2013). "We were interested in developing more potent, novel, chemically modified small molecules to inhibit Rho GTPase activity for possible clinical application in cancer treatment using the Rac1 inhibitor NSC23766 as a lead structure for compound design." (PMID 24040362, 2013). "Previous studies have reported that activation of Rac1 mediated Twist1-induced cancer cell migration." (PMID 24565050, 2013). "Cf-GP-treated cells exhibited significant downregulation of FAK/PI3K/AKT/small GTPase proteins (Rho A, Rac-1, Cdc 42) and mRNA levels compared to the control group, but activation of Rho B induced cancer cells apoptosis." (PMID 23934170, 2013). "By the collective observations, authors proposed that there are likely chances of RAC1 knockdown to affect the tumor cell lung colonization, growth due to a combined effect on cancer cell homing and proliferation in the lung." (PMID 24146998, 2013). "Cdc42 and Rac1 are also crucial in the formation of filopodia and lamellipodia, which are important in the invasion of cancer cells." (PMID 24040362, 2013). "In wound-healing assays, the migrating cancer cells formed lamellipodia where Rac1 and F-actin preferentially co-localized." (PMID 23408967, 2013). "In fact, we showed that ARHGAP11A promotes migration and invasion of cancer cells, by inhibition RhoA and resultant counter-activation of Rac1." (PMID 24386239, 2013). "Wound healing assay showed that migrating cancer cells form lamellipodia at the site of Rac1 localization, with actin filaments organizing the lamella structure." (PMID 23408967, 2013). "A member of the Rho-GTPase family, Rac1, participates in lamellipodia formation and in cancer progression." (PMID 23408967, 2013).